CCL1 (C-C motif chemokine ligand 1)
Diseases named in the same sentence as CCL1 in open-access papers (continued):
Sharing a sentence is not in itself a finding about the gene and the disease.
bladder cancer (2 papers, 2021). "Lastly, CCL1, whose release by fibroblasts has been linked to bladder cancer cell invasion, was significantly diminished." (PMID 34073987, 2021). "For the other CC chemokines, a previous study demonstrated that CCL1 can be up-regulated by estrogen receptors alpha and then enhance bladder cancer cell invasion." (PMID 34893045, 2021). "Besides, GAS5 may inhibit bladder cancer cell proliferation by suppressing the expression of CCL1." (PMID 34893045, 2021).
brain injury (2 papers, 2021 to 2024). Acute and chronic (see also brain INJURIES, CHRONIC) injuries to the brain, including the cerebral hemispheres, CEREBELLUM, and brain STEM. "However, it is still necessary to test whether and how blocking CCR6 and CCR8 affects the activities of their endogenous ligands, which are known to be upregulated, as is well documented for CCL1 and CCL20 after nerve and brain injury, respectively." (PMID 38612597, 2024).
esophageal squamous cell carcinoma (2 papers, 2024). Esophageal squamous cell carcinoma (ESCC) is a type of esophageal carcinoma (EC) that can affect any part of the esophagus, but is usually located in the upper or middle third. "In one study, ANO1-expressing esophageal squamous cell carcinoma cells activated NFκB signaling in fibroblasts, stimulating CCL1 production, and subsequently enhance invasion." (PMID 38352864, 2024).
fibrosis (2 papers, 2020 to 2024). the formation of excess fibrous connective tissue in an organ or tissue in a reparative or reactive process. "Concurrent treatment of hMSCs with a CCL1-blocking antibody alleviated the severity of the lung histopathology score and fibrosis with the preservation of the cutaneous protective effect against CGVHD." (PMID 32586381, 2020).
glioma (2 papers, 2017 to 2023). A benign or malignant brain and spinal cord tumor that arises from glial cells (astrocytes, oligodendrocytes, ependymal cells). "Oxamate treatment decreased Ccl1 and Ccl8 expressions of tumor tissues from glioma implanted nude mice, consistently, CCL1 and CCL18 levels in cultured THP-1 cells in vitro were increased by lactate." (PMID 37770937, 2023).
invasive breast carcinoma (2 papers, 2018 to 2023). A carcinoma that infiltrates the breast parenchyma. "Among them, CCL1 is a major Treg-attracting chemokine in human invasive breast cancer, positively correlated with Treg infiltration and ER-negative high-grade tumors." (PMID 36694223, 2023). "One hundred ninety-nine tissue samples of patients with invasive breast cancer were stained for CCL1 and CCL22 by immunohistochemistry." (PMID 30572845, 2018). "CCL1 was significantly over-expressed in invasive breast cancer as compared to normal breast tissue." (PMID 30572845, 2018). "In summary, we identified CCL1 as a major Treg-attracting chemokine in human invasive breast cancer." (PMID 30572845, 2018). "We therefore aimed at analyzing the roles of the chemokines CCL1 and CCL22 in human invasive breast cancer." (PMID 30572845, 2018).
leukaemia (2 papers, 2015 to 2023). "CCL1 has been implicated in leukaemia and lymphoma, in particular via an autocrine loop that protects cells from apoptosis." (PMID 26439692, 2015). "Compared with the DC-CIKsh-NC group, DC-CIK cells after the knockdown of MMP9 or/and CCL1 significantly promoted the apoptosis of leukemia cells." (PMID 37200633, 2023). "MMP9- and CCL1-silenced DC-CIK cells alone or in combination also further facilitated the apoptosis of the cocultured leukemia cells with activated T cells, especially the combined treatment of MMP9 and CCL1 knockdown in DC-CIK cells." (PMID 37200633, 2023). "Similarly, the results from EdU staining also testified that MMP9- and CCL1-silenced DC-CIK cells displayed the same inhibitory effects on the proliferation of the cocultured leukemia cells with activated T cells." (PMID 37200633, 2023). "Besides, we also uncovered that the cosilencing DC-CIK cells of MMP9 and CCL1 could further enhance the inhibitory effects of MMP9 or CCL1 knockdown on the proliferation of leukemia cells." (PMID 37200633, 2023). "DC-CIK cells with MMP9 and CCL1 knockout alone had little effect on leukemia cells, while knockdown of MMP9 and CCL1 in DC-CIK cells increased cytotoxicity, suppressed proliferation, and induced apoptosis of leukemia cells." (PMID 37200633, 2023). "The CCK-8 results disclosed that DC-CIK cells effectively repressed the proliferation capacities of leukemia cells, and MMP9 or CCL1 knockdown in DC-CIK cells further prevented the proliferation of leukemia cells relative to that in the DC-CIKsh-NC group." (PMID 37200633, 2023). "Due to the promotion of MMP9- and CCL1-silenced DC-CIK cells on the T-cell activation, we further verified the effect of coculture of T cells with leukemia cells on leukemia cell proliferation and apoptosis." (PMID 37200633, 2023). "Next, to investigate whether MMP9- and CCL1-silenced DC-CIK cells can significantly affect the proliferation and apoptosis of leukemia cells, MMP9- or/and CCL1-silenced DC-CIK cells were cocultured with 3 leukemia cell lines." (PMID 37200633, 2023). "Likewise, the EdU staining results also manifested that the proliferation of leukemia cells could be notably suppressed by DC-CIK cells, after MMP9 or/and CCL1 silencing." (PMID 37200633, 2023).
lung diseases (2 papers, 2015 to 2022). "This work not only expands our knowledge of CCL1 biology, but also sheds new light on therapeutic strategies for curing fibroproliferative lung diseases." (PMID 34940827, 2022).
lymphoma (2 papers, 2012 to 2015). A malignant (clonal) proliferation of B- lymphocytes or T- lymphocytes which involves the lymph nodes, bone marrow and/or extranodal sites. "CCL1 is a potent protector of T lymphoma cells against DEX-induced apoptosis." (PMID 22479563, 2012). "Therefore, we wondered if the T lymphoma cells were capable of influencing the anti-apoptotic trigger of CCL1 by expressing CPM at the cell surface as a response to the presence of DEX and/or CCL1." (PMID 22479563, 2012). "We hypothesized that the T lymphoma cells could augment their CPM expression when in contact with DEX, thereby enhancing the possibility of the formation of truncated CCL1 if contact with CCL1 would occur." (PMID 22479563, 2012). "The T lymphoma cells that we tested did not respond to DEX and/or CCL1 by enhancing their CPM expression at the cell surface." (PMID 22479563, 2012).
osteoarthritis (2 papers, 2021 to 2022). A noninflammatory degenerative joint disease occurring chiefly in older persons, characterized by degeneration of the articular cartilage, hypertrophy of bone at the margins and changes in the synovial membrane. "For instance, a recent study showed that circ_0134111 could induce osteoarthritis development through regulating miR-224-5p/CCL1 and miR-515-5p-SOCS1 axes." (PMID 35136049, 2022).
ovarian tumor (2 papers, 2023). "The CCR8-CCL1 and CCR8-CCL18 axis also plays a major role in the migration and infiltration of CD4+CCR8+ Tregs into ovarian tumor tissues that significantly overexpress CCL1 and CCL18 ligands (S. 27)." (PMID 38264664, 2023). "The ligands CCL1 and CCL18 corresponding to CCR8 were significantly overexpressed in ovarian tumor tissues, and the CCR8-CCL1 and CCR8-CCL18 axis played a key role in the migration and infiltration of CD4+CCR8+ Tregs into ovarian tumor tissues." (PMID 37950246, 2023).
parasite infection (2 papers, 2020 to 2022). "During type 2 polarized immune responses e.g. induced by parasitic infections or atopic diseases, CCL1 has been shown to be primarily produced by mast cells and ILC2s most likely by stimulation via alarmins, such as IL-33." (PMID 33613532, 2020).
rheumatoid arthritis (2 papers, 2019 to 2021). A chronic, systemic autoimmune disorder characterized by inflammation in the synovial membranes and articular surfaces. "In fact, CCL1,2,5 is reported to cause strong association for recruitment monocytes/macrophages in immunological diseases such as rheumatoid arthritis and cardiovascular diseases." (PMID 33671612, 2021).
tuberculous pleurisy (2 papers, 2012 to 2021). "Our data show that CCL1, CXCL9 and IP-10 were highly expressed in both the periphery and the pleural effusions from tuberculous pleurisy patients." (PMID 23028695, 2012). "Our data suggests that compared to patients without TPE, patients with tuberculous pleurisy have a threefold higher chance of being CCL1 assay positive." (PMID 33436672, 2021). "Moreover, among the examined factors, CCL1, CCL21 and IL-6 were markedly increased in pleural effusions from tuberculous pleurisy patients and the supernatants of cultured PFMCs after M.tb-specific antigen stimulation." (PMID 23028695, 2012).
acute disseminated encephalomyelitis (1 paper, 2022). Acute disseminated encephalomyelitis (ADEM) is a demyelinating disorder of the central nervous system. "Unlike MS, elevated neutrophil chemokines (CXCL7) and Th2 cell chemokines (CCL1, CCL22, and CCL17) were also found in the CSF of acute disseminated encephalomyelitis (ADEM), another inflammatory demyelinating disease, helping to differentiate ADEM from MS." (PMID 35837284, 2022).
adult T cell leukemia (1 paper, 2012). "The existence of an autocrine anti-apoptotic loop in adult T cell leukemia cells (ATLs) mediated by the overexpression of CCL1 was suggested." (PMID 22479563, 2012).
atopic dermatitis (1 paper, 2023). "CCL1 is an inflammatory factor associated with the inflammatory response in atopic dermatitis." (PMID 37200633, 2023).
breast tumor (1 paper, 2024). "The tremendous impact of CCL1 on the accumulation of Tregs in the breast tumor environment is evident, as CCL1 serves as the functional ligand for CCR8." (PMID 38730579, 2024).
Cirrhosis (1 paper, 2025). A chronic disorder of the liver in which liver tissue becomes scarred and is partially replaced by regenerative nodules and fibrotic tissue resulting in loss of liver function. "However, CCL1 was only associated with lean cirrhosis in this comparison, whereas CXCL8 did not exhibit statistical significance in either the lean or overweight cirrhosis groups." (PMID 40995436, 2025). "Compared with the GRS 0–4 group, patients with cirrhosis with GRS 5–8 exhibited increased levels of MMP2 (FDR <0.05), CCL1, and CXCL8 (p <0.05)." (PMID 40995436, 2025).
Cognitive impairment (1 paper, 2023). Abnormal cognition is characterized by deficits in thinking, reasoning, or remembering. "However, new data on CCL1 levels in CSF did not corroborate the finding that CCL1 in CSF, but not in blood, is linked with the severity of cognitive impairment." (PMID 37291639, 2023). "Chemokines CCL1, CCL2, CCL15, CCL27, CXCL9, CXCL10, and CX3CL1 might be most promising to serve as key molecular markers of cognitive impairment, although more cohort studies with larger populations are needed." (PMID 37291639, 2023).
colorectal cancer (1 paper, 2023). A primary or metastatic malignant neoplasm that affects the colon or rectum. "In addition, six homeostatic chemokines, CXCL12, CCL1, CCL20, CCL25, CCL27, and CXCL11, were upregulated in the peripheral blood of patients with advanced colorectal cancer, which has also been reported to be associated with tumor progression." (PMID 37063892, 2023).
dyslipidemia (1 paper, 2024). "The progressive rise in blood concentrations of three pro-inflammatory chemokines CCL-1, 2, and 4 in T2DM subjects with increasing BMI supports the idea that dyslipidemia and obesity contribute to chronic inflammation and insulin resistance." (PMID 39063997, 2024).
encephalomyelitis (1 paper, 2014). Inflammation of the brain and the spinal cord. "In addition, CCL2 can supplement T-cell activation-3/CCL1, the ligand of the CCR8 receptor, to guide the infiltration of T cells in encephalomyelitis." (PMID 25009636, 2014).
graft versus host disease (1 paper, 2023). An immune system disorder that occurs after allogeneic hematopoietic stem cell transplant and is a reaction of donor immune cells against host tissues. "CCL1 is upregulated in human mesenchymal stem cell (hMSC)-induced PF in the murine sclerodermatous graft-versus-host disease (Scl-GVHD) model." (PMID 36830702, 2023).
heart failure (1 paper, 2021). Inability of the heart to pump blood at an adequate rate to meet tissue metabolic requirements. "CCL1 is a potent chemoattractant for monocytes and macrophages, and is involved in stimulating pathological inflammation in heart failure patients." (PMID 33753732, 2021).
hyperglycaemia (1 paper, 2016). "In the diabetic mice, the detection of adiponectin production or elevated levels of inflammatory factors such as CCL1 and TPO expression were found to reduce hyperglycaemia and thereby induce an inflammatory response." (PMID 27378920, 2016).
influenza infection (1 paper, 2021). "Interestingly, cells that traffic from the spleen after influenza infection have previously been shown to produce CCL1 and GM-CSF, so it is intriguing that this profile of protection is conserved within the cells already present within the lungs." (PMID 34566986, 2021).
Insulin resistance (1 paper, 2024). Increased resistance towards insulin, that is, diminished effectiveness of insulin in reducing blood glucose levels. "CCL1 is believed to have the dual purpose of predisposing subjects to both obesity and insulin resistance; this assumption seems plausible in light of the significantly higher levels of CCL1 in T2DM subjects in all four groups, A to D, ranging from normal body weight to severe obesity." (PMID 39063997, 2024).
ischemia (1 paper, 2022). A hypoperfusion of the BLOOD through an organ or tissue caused by a PATHOLOGIC CONSTRICTION or obstruction of its BLOOD VESSELS, or an absence of BLOOD CIRCULATION. "Moreover, it has been shown, in an in vivo model of ischemia, that CCL1 produced by astrocytes and oligodendrocytes attracts Treg cells to the ischemic brain." (PMID 35892669, 2022).
liver fibrosis (1 paper, 2024). "Hence, the inhibition of CCL2/CCR2, CCL5/CCR5, and CCL1/CCR8 chemotaxis shows potential efficacy to repair liver fibrosis." (PMID 39635524, 2024). "In the progress of liver fibrosis, peripheral pro-inflammatory mononuclear MoMφs can be attracted to the liver depending on CCL2/CCR2, CCL5/CCR5, and CCL1/CCR8 chemokines axis and aggravate liver fibrosis." (PMID 39635524, 2024).
liver steatosis (1 paper, 2023). "Thus, this CCL1-dependent alteration in macrophage accumulation may account for the amelioration of liver steatosis induced by miR-21a-5p." (PMID 39872853, 2023).
malignant glioma (1 paper, 2012). A grade III or grade IV glioma arising from the central nervous system. "CCL1-mediated Ca2+i mobilization through CCR8 has been described in cells expressing the receptor endogenously, e.g. monocytes, HL-60 clone 15, IL-2-activated natural killer cells, T cell lines, BW5147 cells, and U87 malignant glioma cells." (PMID 22479563, 2012).
meningeal TB (1 paper, 2012). "Among potential clinical signatures reported are CXCL9, CXCL10, CCL1, and IL11, as their expression levels could differentiate some kinds of clinical manifestations such as latent TB, pulmonary, and meningeal TB." (PMID 22675550, 2012).
metastatic melanoma (1 paper, 2015). A melanoma that has spread from its primary site to another anatomic site. "This study showed that blocking CCR8 or CCL1 inhibits tumor cell migration to lymphatic endothelial cells and that CCR8 is also expressed in human metastatic melanoma." (PMID 25853550, 2015).
Miscarriage (1 paper, 2018). A pregnancy that ends at a stage in which the fetus is incapable of surviving on its own, defined as the spontaneous loss of a fetus before the 22th week of pregnancy. "The additional characterization of the macrophage polarization status using the M1 polarization markers TLR2 and iNOS and the M2 polarization markers CCL1 and CX3CR1 confirmed the loss of M2 polarized marcrophages in recurrent miscarriages." (PMID 29949879, 2018).
Myelopathy (1 paper, 2017). Myelopathy is an descriptive term, referring to pathology leading to a neurologic deficit related to the spinal cord. "Because CCL1 is also known as a potent chemoattractant that plays a major role in inflammatory processes, we investigated the role of CCL1 in the pathogenesis of human T-cell leukemia virus type 1 (HTLV-1)-associated myelopathy/tropical spastic paraparesis (HAM/TSP)." (PMID 29202792, 2017).
neuropathy (1 paper, 2023). A disorder affecting the nervous system that manifests with pain, tingling, numbness, and/or muscle weakness. "Moreover, CCL1/CCR8 signaling is suggested to be important for the development of neuropathic pain, since the spinal upregulation of CCL1 was demonstrated in STZ-, CCI- and PSNL-induced neuropathy." (PMID 37570736, 2023).
Obesity (1 paper, 2024). Accumulation of substantial excess body fat. "Using a T2DM and a control cohort from the Asir region of Saudia Arabia, we looked into the association between the pro-inflammatory chemokines CCL1, CCL2, CCL4, and CCL5 and the etiopathogenesis of T2DM in subjects with different degrees of obesity, BMI, and HbA1c." (PMID 39063997, 2024). "With this background, we intend to study the relationship between pro-inflammatory chemokines CCL1, CCL2, CCL4, and CCL5 and the etiopathogenesis of T2DM in subjects with varying levels of obesity, BMI, and HbA1c in a patient cohort from the Asir region of Saudia Arabia." (PMID 39063997, 2024).
oral cancer (1 paper, 2021). "CCL1 and CCL18 may either play a role in CCR8+ Treg migration to the malignant zone of oral cancer or they might induce its expression directly, thus, we measure chemotaxis and CCR8 induction in response to recombinant chemokines CCL1 and CCL18." (PMID 34025655, 2021).
ovarian carcinoma (1 paper, 2023). A malignant neoplasm originating from the surface ovarian epithelium. "Chemotactic assays in vitro suggested that high level of CCL1 and CCL18 in the TME of ovarian cancer contributed to the increased infiltration of CD4+CCR8+ Tregs into tumor tissues." (PMID 37950246, 2023). "Therefore, we believe that the high expression of CCL1 and CCL18 in ovarian cancer TME is an important factor in the increase of CD4+CCR8+ Tregs infiltration into tumor tissues." (PMID 37950246, 2023).